OLIG2 (oligodendrocyte transcription factor 2)
Diseases named in the same sentence as OLIG2 in open-access papers (continued):
Sharing a sentence is not in itself a finding about the gene and the disease.
tumor (continued). "Previous studies have predominantly focused on Olig2, highlighting its roles in the reprogramming of GBM cells, resistance to genotoxic therapy, and the plasticity of tumor phenotypes." (PMID 40428395, 2025). "A heatmap was generated to depict the expression profiles of ATRX, OLIG2, MGMT, and IDH2 in normal and tumor tissues, using Log2(TPM+1) for scaling." (PMID 40282990, 2025). "The primary histological findings suggested a proliferative active tumor with co-expression of epithelial membrane antigen (EMA), oligodendrocyte transcription factor (Olig2), and elevated Ki67-proliferation index." (PMID 39953192, 2025). "Boxplots depict the protein expression levels (Z-values) of ATRX, OLIG2, MGMT, and IDH2 in normal tissue samples (n = 10, blue) and primary tumor samples (n = 99, red)." (PMID 40282990, 2025). "A significant upregulation of ATRX, OLIG2, and downregulation of IDH2 at protein level was observed in GBM tumor samples compared to normal tissues, with p-values indicating statistical significance (**** p < 0.0001; *** p < 0.001)." (PMID 40282990, 2025). "Our findings underscore the significance of Olig2 as a central developmental regulator in GBM, highlighting the need for further studies to elucidate its role in tumor heterogeneity." (PMID 40282990, 2025). "We first localized the tumor core within the full-brain sagittal sections using the canonical DMG neoplastic cell markers Olig1, Olig2, and Pdgfra." (PMID 40244686, 2025). "Immunohistochemical markers commonly observed in intraventricular DMG tumor case reports, were GFAP, Olig2, Ki67, and S100, were also expressed." (PMID 40182052, 2025). "We observed a significant reduction in the number of Ki67, Olig2- and SOX2-positive cells in the mubritinib-treated mice, indicating that mubritinib alters proliferation and stemness in GB tumours in vivo." (PMID 39901019, 2025). "We observed GFP in oligodendrocytes positive for oligodendrocyte transcription factor 2 (OLIG2) and neurons expressing NEUN, a mature neuronal marker at the tumor periphery." (PMID 39563028, 2025). "Relative to vehicle (PBS)-treated controls, NFκB inhibition reduces tumor proliferation (%Ki67+ cells), BLBP+ and Olig2+ cells (%Olig2+ and %Blbp+ cells) and Ccl5 expression at 12 weeks of age." (PMID 38308315, 2024). "In one case series, an OLIG2 IHC cut-off of 3% was proposed, with positivity below this value suggesting an H3G34-altered tumour." (PMID 39126064, 2024). "The tumor was diffusely positive for glial markers (GFAP and OLIG2) and there was widespread expression of synaptophysin." (PMID 38650040, 2024). "Analysis of tumor spheres has revealed co-expression of ITGA6 with the tumor stem cell markers CD133, nestin, and Olig2." (PMID 39239559, 2024). "To understand the role of C3 and complement in the tumor microenvironment, we returned to stain the murine GBMs for C3, GFAP, Olig2, and Nestin to highlight perivascular tumor areas." (PMID 39172519, 2024). "Co-localization analysis of ASCL1 and OLIG2 double+ cells in terminal tumors showed that while only 64% of OLIG2+ tumor cells are ASCL1+, 86% of ASCL1+ tumor cells were OLIG2+." (PMID 39609428, 2024). "The transcription factor OLIG2 facilitates the migration of NPC-like and OPC-like tumor cells along vessels and white matter tracts." (PMID 38473812, 2024). "As expected, OPC markers OLIG2, SOX9, and cell cycle genes CDK1, MKI67 are highest in the tumor core (early peak), while neuronal markers ZIC1, GABRA1, and mature oligodendrocyte marker MBP are highest in the GCL_N (late peak)." (PMID 36823172, 2023). "Tumors were diffusely infiltrative, and GFP+ tumor cells clearly colocalized with H3K27M and Ki-67 and expressed high levels of neural stem/progenitor cell markers OLIG2 and Nestin." (PMID 37011011, 2023).
tumor (continued). "Here, we demonstrate that GCS-enriched spheres from WG14 expressed significantly higher levels of OLIG2 and lower levels of astrocytic (GFAP) and neuronal (β-Tubulin III) markers as compared with the adherent tumor cells." (PMID 36900355, 2023). "Within the murine tumor, senescent cells were of distinct types, and included either malignant (GFP+) tumor cells, glial cells (GFAP+, OLIG2+), or microglia/macrophage (IBA1+)." (PMID 36707509, 2023). "High grade tumors have a higher Ki67 proliferation index indicative of more aggressive tumor growth and they tend to exhibit high immunoreactivity for stem cell markers such as CD133, Nestin, Sox2 and Olig2." (PMID 37920169, 2023). "Immunostaining has shown positive staining for glial markers such as GFAP and Olig2, albeit with weak or focal expression, but CD34 expression was notably prominent and consistently observed across tumor cells and neuronal elements." (PMID 38137148, 2023). "The results on BAL B/c mice indicated that the tumor growth, tumor volume, tumor weight, and CD133 expression was significantly increased in Olig2 overexpression group versus vector control group." (PMID 36990974, 2023). "In comparing the tumor core and edge regions, we found statistically significant elevations in proliferative marker Ki-67 as well as glial progenitor markers SOX2, Olig2, and NG2, (p < 0.05)." (PMID 37752585, 2023). "A subset of cells stained positive for OLIG2 and SOX10, with approximately 20% of cells staining positive for each of these markers in some areas of the tumor." (PMID 35484611, 2022). "To confirm that the subependymal and intraventricular tumor recapitulates the biology of HGG, we performed Olig2 and Ki67 immunohistochemistry." (PMID 35733516, 2022). "Olig2 is an oligodendrocyte-specific transcription factor expressed at all stages of oligodendrocyte development, and APC is a tumor suppressor that is transiently expressed during myelination and remyelination." (PMID 36430692, 2022). "Immunohistochemical analysis showed the expression of GFP was retained in tumor cells uniformly and at high levels and cells retained defining lineage markers of DMG including diffuse Olig2 and Gfap labeling." (PMID 35105861, 2022). "Immunohistochemical analysis of GBM sections obtained from the core and periphery of the tumor, as well as GSCs isolated from these two regions, showed that the invasion edge expresses high levels of the CD133 and Olig2 PN markers relative to the tumor core." (PMID 35205179, 2022). "In fact, the low levels of OLIG2 and SOX10 immunostaining seen in this tumor are more consistent with what has been reported for subepenymomas." (PMID 35484611, 2022). "Tumor cells are strongly immunoreactive for a glial fibrillary acid protein (GFAP), Olig2, and S100." (PMID 34065573, 2021). "In contrast to SETMAR protein isoforms, snRNP70, OLIG2 and PTN protein levels were lower inside the necrotic area, while being detected at higher levels within the tumor region." (PMID 35047379, 2021). "Western blot analysis of whole tumor extracts demonstrated decreased expression of the human-specific GSC markers SOX2 and OLIG2 and reduced levels of p-STAT3 compared with the controls." (PMID 33986188, 2021). "In GBM, the overexpression of the ZEB1 gene induced the expression of MGMT, resulting in greater tumor chemoresistance and also induced the expression of SOX2 and OLIG2, resulting in greater stemness and higher capacity for tumor formation." (PMID 33762015, 2021). "We also evaluated the correlations between the expression of DCX, OLIG2, and NES genes at a single-cell level in the population of cells derived from the tumour tissue to show the potential relation of these genes." (PMID 34948016, 2021). "High magnifications revealed that ASCL1, OLIG2, and SOX2 are also expressed specifically within the YFP+ tumor cells, which are highly irregular in shape, morphology, and density compared to normal YFP+ cells on the nontumor side (not shown)." (PMID 32573857, 2020).
tumor (continued). "Both the patient and the PDX tumours were positive for OLIG2, nestin, vimentin and GFAP, with focal Ki-67 proliferative indices of up to 25% in the patient tumour and 40% in PDX tumours, respectively." (PMID 33053751, 2020). "Similar to the early tumors and the PDX‐GBMs, ASCL1, OLIG2, and SOX2 were coexpressed in the tumor cells of these terminal tumors, and many ASCL1+ tumor cells were also Ki67+." (PMID 32573857, 2020). "Isolated GSCs were characterized by the expression of the GSC markers (SOX2, OLIG2, CD133, L1CAM) and functional assays including serial neurosphere formation assay, in vitro cell differentiation assay and in vivo limiting dilution tumor formation assay." (PMID 32541784, 2020). "L1CAM knockdown decreased OLIG2 expression and upregulated the CDKN1 (also known as p21) tumor suppressor in CD133+ glioma cells." (PMID 32722427, 2020). "Two additional OLIG2 positive cases showed inconclusive FISH results, but were positive for TFAP2B and ALK, what suggests that these tumours expressed fusion positive signature." (PMID 31493794, 2019). "The tumor cells composed of perivascular pseudorosettes showed positivity for both synaptophysin and glial markers such as GFAP and Olig2." (PMID 31804365, 2019). "CT and PVZ cells expressed neural tumor stem cell markers CD133, NESTIN, OLIG1, OLIG2, SOX2 and A2B5." (PMID 30333910, 2018). "The results indicate a differential stability of the CD133/Olig2 and CD44 GBM cell subpopulations with implications for the evolution of resistant subpopulations and tumor recurrence." (PMID 28241049, 2017). "To investigate PTPRZ1 expression pattern in GBMs, we co-immunostained PTRPZ1 and several GSC markers in frozen GBM specimens and found a preferential expression of PTPRZ1 in tumour cells expressing GSC markers SOX2, OLIG2 and CD133." (PMID 28569747, 2017). "Immunohistochemistry demonstrates tumor cells were positive for GFAP, OLIG2, SOX2, IDH1(R132H) and a MIB1 proliferation index of >30 %." (PMID 26817999, 2016). "Endoxifen-induced tumours expressed GFAP, nestin, Sox2, Olig2, PDGFRa and doublecortin (Fig. 5E1-J1), and were indistinguishable from tumours generated by Adeno-Cre or Adeno-GFAP-Cre injection and as shown in Fig. 5E2-J3." (PMID 26704996, 2016). "Next, we examined tumor biopsies from patients (n = 29) using immunohistochemistry to investigate the patterns and intensities of LIN28, OLIG2, and Rad51 expression." (PMID 27074032, 2016). "Tumour-derived cultures are usually similar to neural stem cell cultures in that NES-, GFAP-, OLIG2- and TUBB3-positive cells are all present." (PMID 27991551, 2016). "Immunohistochemical (IHC) analysis showed diffuse expression of GFAP, OLIG2 and SOX2 consistent with a tumor of glial lineage." (PMID 26817999, 2016). "Of these genes, Pax3, Irx5, and Chl1 were also differentially regulated between the Olig2-compartments of BSG and CG suggesting that they represent biological differences within the tumor cells." (PMID 25330836, 2014). "The GFP-positive fractions were analyzed for gene expression differences by microarray, and 118 genes were found differentially regulated between Olig2-BSG and Olig2-CG tumor cells." (PMID 25330836, 2014). "OLIG2 has also been characterized as a key dependency in GBM, regulating a neurodevelopmental transcriptional program key in gliomagenesis and maintenance of different tumor cell states." (PMID 41501023, 2026). "Additionally, both treatments resulted in reduced tumor-related architectural tissue distortion, CD8+ T cell infiltration, Olig2+ cell content, and BLBP+ cell content." (PMID 41497446, 2025).
tumor (continued). "Histologic findings of Olig2 positivity with focal to absent GFAP warrant further evaluation for this tumor entity." (PMID 40724977, 2025). "In the control group, GFP+ tumor cells exhibited high expression of OLIG2 but lacked the expression of the oligodendrocyte marker SOX10." (PMID 40428395, 2025). "Given that the GSC state is not a stable clonal subpopulation but rather a plastic state induced by the tumor microenvironment, we scored cells based on classic GSC markers (PROM1, SOX2, NES, OLIG2, BMI1, NANOG, POU5F1) and defined the top 2% of cancer cells with the highest stemness scores as GSCs." (PMID 41041071, 2025). "EGFR and IDH1 were highly expressed in tumor cells, FAP and COL1A1 were confined to fibroblasts, CD68 and ITGAM marked macrophages, PECAM1 and CDH5 identified endothelial cells, OLIG2 and MOG were specific to oligodendrocytes, while CD4 and CD3D defined T-cell subsets." (PMID 41208987, 2025). "Interestingly, some MDI-2268/lucanthone combination treatment effects were intermediate rather than additive: namely, in PAI-1 activity with lower concentrations, in Olig2 protein levels in GSC, and in tumor vascularization." (PMID 40684232, 2025). "Tumor cells exhibited variable immunoreactivity for GFAP and were positive for Olig2." (PMID 40469416, 2025). "Tumor cells typically showed strong immunoreactivity for GFAP and Olig2." (PMID 40469416, 2025). "Then, we conducted SCENIC analysis to explore the transcriptional regulation driving the acquisition of the cholesterol-related Tumor-Modifying state in neutrophils which revealed activation of BHLH family transcription factors (BHLHE40, ETV5, OLIG2, and SREBF1) within the Neu-T-CCL3 cluster." (PMID 38822440, 2024). "Loss- and gain-of-function combined with scRNA-seq reveal that tumor cells with higher levels of ASCL1 relative to OLIG2, as seen in the Olig2-CKO and Ascl1-OE tumors, favor activation of a NSC/astrocyte program, characterized by high expression of GFAP and a highly migratory or diffuse phenotype." (PMID 39609428, 2024). "The tumor cells were negative for GFAP, Olig-2, and only individual tumor cells expressed synaptophysin." (PMID 38926750, 2024). "The tumor cells diffusely expressed OLIG2, synaptophysin, MAP2, NeuN (not shown) and SOX10 but did not express GFAP." (PMID 38926880, 2024). "Immunohistochemically, tumor cells express glial markers (i.e., GFAP and OLIG2) and CD34, which may be patchy or diffuse and may also display non-neoplastic ramified neural elements in the associated cerebral cortex." (PMID 38544524, 2024). "This migration difference could be due in part to the manner of tumor induction and/or tumor cell-of-origin, or possibly due to the low levels of Ascl1 in these adult OPC-induced Olig2-CKO tumors, as revealed by bulk RNA-seq33." (PMID 39609428, 2024). "Immunostaining revealed that the tumor cells were negative for glial fibrillary acidic protein and oligodendrocyte transcription factor 2, but they were diffusely positive for CD56 and S100 protein." (PMID 38255255, 2024). "However, we found that tumor BCAS1+ cells express other oligodendroglial markers (i.e., OLIG2 and SOX10) related to immature stages within the oligodendrocyte linage." (PMID 38275289, 2024). "In contrast, our findings show nearly universal staining of pan-oligodendrocyte lineage markers OLIG2 and SOX10, OPC makers PDGFRA and NG2 and developing oligodendrocyte marker Nogo-A in the tumour cells of DNET, MGNT and RGNT samples and an enrichment of OPC signature in DNET transcriptomes." (PMID 38764775, 2024). "Consequently, affected radial glia are then transformed into tumor-propagating NPCs marked by dynamic levels of ASCL1 and OLIG2." (PMID 39609428, 2024). "This discrepancy was also observed within control tumors but in the opposite direction, whereby many SOX10+ tumor cells are negative for OLIG2." (PMID 39609428, 2024).
tumor (continued). "Additionally, PepO treatment also resulted in a decrease in the tumor stem cell-related proteins ABCG2, OCT4, SOX2 and Olig2." (PMID 37925462, 2023). "Considering that the bulk of proliferative tumor cells in G-Smo MBs were not OLIG2-expressing tumor stem cells, we anticipated that CT-179 would be more effective when combined with a more broadly directed therapy." (PMID 37333134, 2023). "Simultaneously, the subcutaneous xenografts model result indicated that the tumor growth rate, tumor volume and tumor weight were significantly decreased in Olig2 knockdown group versus negative control group." (PMID 36990974, 2023). "Additionally, we implanted NCI-H820 tumor pieces into the right flank of female BAL B/c nude mice, and intra-tumoral injected pCMV-N-Flag or pCMV-N-Flag-Olig2 in lipofectamine 2000 solution." (PMID 36990974, 2023). "Histological evaluation of qMCP-deficient and WT tumors showed reduction of tumor-associated macrophages by IBA1 staining with no changes in P2RY12, CD31, OLIG2, GFAP, and CD44 positive areas." (PMID 37012245, 2023). "On the other hand, CELF2 expression is inversely correlated with that of miR-199a-3p, which is expressed in differentiated GBM cells and in OLIG2-negative, low-mitotic index tumor territories." (PMID 37894405, 2023). "Tumor cells were predominantly negative for OLIG2 and synaptophysin, positive for GFAP and demonstrated intracytoplasmic dot-like EMA staining." (PMID 36937401, 2023). "Glial markers, Olig2 and GFAP, were expressed in both tumour types." (PMID 36264505, 2022). "Moreover, YAP was enriched at the promoter regions of several key factors involved in the stemness of tumor cells, such as SOX9, SMAD2/4, OLIG2, and MYC." (PMID 35322024, 2022). "In contrast, many SHH-1A and SHH-1B cases stained positive for OLIG2 [9/22 (41%) and 8/12 (67%), respectively], whereas positive OLIG2 staining (> 5% of tumor cells) was not encountered in any SHH-2 [0/23 (0%); Chi-Square: 18.849; df: 2; P < 0.001]." (PMID 35501487, 2022). "Tumor cells were negative for Olig2, synaptophysin, chromogranin, neurofilament, NeuN, epithelial membrane antigen, CD34, IDH1 (R132H), Melan A, and Inhibin alpha." (PMID 35209854, 2022). "GFAP and OLIG2 were positive in all primary tumors (10/10) with one tumor showing a mixture of positive and negative cells whereas all others showed widespread positivity." (PMID 34967922, 2022). "Lack of OLIG2 expression is one of the characteristics of this tumor and was previously reported in 100% of G34 DHGs." (PMID 35109850, 2022). "Immunohistochemical staining revealed that the tumor cells were positive for S-100 protein and negative for Olig2." (PMID 35209854, 2022). "Examination of lineage-specific marker expression revealed four principal clusters corresponding to tumor and glia (using the SOX2, OLIG2, GFAP markers), lymphoid cells (CD45, CD3, CD8, and CD4), myeloid cells (CD45, PU.1, CD163, CD68, and CD11b), and endothelial cells (CD31)." (PMID 35973991, 2022). "Histopathologically, the tumor was paucicellular with subependymal features and without Olig2 immunopositivity." (PMID 36104744, 2022). "This type of tumor demonstrates strong immunoreactivity for GFAP, S100, and Olig2." (PMID 34065573, 2021). "In contrast to the salient OPC features in glioma, the tumor cells in our disease model do not abundantly express differentiated cell markers such as Olig2, S100β, and CC1." (PMID 33863883, 2021). "Our data also support the notion that there is a set proportion of cells expressing DCX/NES/OLIG2, regardless of treatment, guided by tumour plasticity." (PMID 34948016, 2021). "These annotations were used to predict the role of DCX, OLIG2, and NES in tumour biology." (PMID 34948016, 2021).